SFRP4 (secreted frizzled related protein 4)
Diseases named in the same sentence as SFRP4 in open-access papers (continued):
Sharing a sentence is not in itself a finding about the gene and the disease.
breast carcinoma (11 papers, 2008 to 2025). "Screening, different databases utilising the sFRP4 target protein, investigation of diverse in-silico methodologies for modulating the molecular pathways linked to the progression of breast cancer, and the molecule’s confirmation in in vitro experiments." (PMID 40920763, 2025). "Gene expression research indicated aberrant sFRP4 expression in a diversity of malignancies, including breast cancer." (PMID 40920763, 2025). "Silibinin and Isotretinoin impede cancer cell development in vitro; nonetheless, this study demonstrated that they directly upregulate sFRP4 and induce apoptosis in breast cancer cells." (PMID 40920763, 2025). "An effective method for blocking the Wnt signalling pathways’ beta-catenin compensation mechanism is to target sFRP4 in breast cancer." (PMID 40920763, 2025). "This study is based on the analysis of expression profiles, which demonstrated that the sFRP4 gene exhibits aberrant expression in multiple cancers, including breast cancer." (PMID 40920763, 2025). "Restoring sFRP4 expression presents a favourable therapeutic approach for mitigating breast cancer progression." (PMID 40920763, 2025). "DIO has been reported to inhibit breast cancer stem-like cells by deregulating the activation of Wnt/beta-catenin signaling via sFRP4." (PMID 32664914, 2020). "Furthermore, we found that Silibinin can upregulate the expression of the sFRP4 gene and suppress the Wnt/β-catenin signaling pathway in breast cancer cells." (PMID 40920763, 2025). "The case for sFRP4 as a breast cancer therapeutic target is becoming stronger by the day." (PMID 40920763, 2025). "Interestingly, both DKK-1 and sFRP4 are antagonists of the Wnt signaling pathway, but the effect of CBX7 in regulating sFRP4 in colon cancer is quite different from the effect of regulating DKK-1 in breast cancer." (PMID 34659360, 2021). "Recently, ursolic acid has been shown to decrease the β-catenin levels by increasing the level of Wnt antagonists, sFRP4 and DKK1, in breast cancer stem-like cells." (PMID 34584036, 2021). "Diosgenin has also been reported to inhibit breast cancer stem-like cells through suppression of the Wnt/β-catenin signaling pathway via targeting sFRP4 (secreted frizzled-related protein 4), leading to attenuation of EMT and invasion in breast cancer." (PMID 32626765, 2020). "The distinct cell-cell communication patterns and different pseudo development trajectory indicate that SFRP4+ CAF may have a unique biological function and role in breast cancer." (PMID 38686196, 2024). "Furthermore, we established that elevated expression levels of SFRP4+ CAF markers correlate with improved survival outcomes in BC patients, yet paradoxically, they predict a diminished response to neoadjuvant chemotherapy in cases of triple-negative breast cancer." (PMID 38686196, 2024). "Furthermore, single cell RNA-sequencing in breast cancer suggests that SFRP2 and SFRP4 expression is restricted to cells identified as stromal." (PMID 28218291, 2017). "Not surprisingly, like CBX7 in breast cancer, abnormal activation of the Wnt signaling pathway is found in 90% of colon cancer, and one of the reasons may be the absence of secreted frizzled-related protein 4(sFRP4)." (PMID 34659360, 2021).
colorectal cancer (11 papers, 2009 to 2026). A primary or metastatic malignant neoplasm that affects the colon or rectum. "For the TCGA-COAD dataset, 2 of the top genes selected by the model, SFRP4 and ANGPTL1, are known to be highly expressed in colorectal cancer (CRC) and have been linked to poor clinical outcomes in patients with CRC." (PMID 41363728, 2026). "For the TCGA-COAD dataset, two of the top genes selected by the model—SFRP4 and ANGPTL1—are known to be highly expressed in colorectal cancer (CRC) and have been linked to poor clinical outcomes in CRC patients." (PMID 40093058, 2025). "Previous research has found that SFRP4 is highly expressed in colorectal cancer patients and that individuals with high SFRP4 expression have a worse prognosis than those with low SFRP4 expression." (PMID 35847366, 2022). "It has been reported that the protein expression of sFRP4 was downregulated through promoter CpG island methylation in colorectal cancer, mesothelioma, cervical cancer and leukemia." (PMID 25844602, 2015). "Previous evidence clearly showed that the expression of SFRP4 (secreted frizzled-related protein 4) was up regulated in colorectal cancer tissues, but down regulated in other cancer types; we found it to be upregulated in HCC tissues." (PMID 23483081, 2013). "SFRP4 has been found frequently methylated in colorectal cancer and in chronic lymphocytic leukemia." (PMID 20111589, 2009).
Pyle disease (11 papers, 2017 to 2023). A bone dysplasia characterized by genu valgum, metaphyseal anomalies with broadening of the long bones extending into the diaphyses and giving the femora and tibiae an 'Erlenmeyer flask'' appearance, widening of the ribs and clavicles, platyspondyly and cortical thinning. "Sfrp4 KO mice show similar skeletal architecture and bone fragility deficits observed in patients with Pyle’s disease with SFRP4 mutations." (PMID 36808149, 2023). "In these cells, the expression of Sfrp4, a gene associated with bone cortical formation or remodeling, was significantly reduced; interestingly, SFRP4 variants lead to Pyle disease, a bone disorder characterized by thinning of the cortex." (PMID 37484945, 2023). "The dysregulation of Wnt signaling due to SFRP4 mutation leads to the bone abnormalities characteristic of Pyle disease." (PMID 35163424, 2022). "Mutations in SFRP4 are linked to metaphyseal dysplasia or Pyle’s disease, characterized by a thinning of the cortical bone, limb deformity and bone fracture." (PMID 35052478, 2022). "Pyle disease is a monogenic disease that is inherited in an autosomal recessive pattern, where both copies of the secreted frizzled-related protein 4 gene (SFRP4) are mutated." (PMID 35163424, 2022). "Filtering of the exome-sequencing data from patients diagnosed as Pyle's disease resulted in the discovering of the underlying genetic defect as SFRP4 deficiency." (PMID 34484289, 2021). "Herein, we report on two siblings clinically diagnosed with Pyle disease caused by two novel compound heterozygous missense mutations in the SFRP4 gene that were detected in both patients using whole-genome sequencing approach (WGS)." (PMID 33193738, 2020). "To conclude, herein, we report on the first SFRP4 missense mutations in compound heterozygosity resulting in Pyle disease." (PMID 33193738, 2020). "Since 2016, various bi-allelic truncating mutations in sFRP4 have been confirmed to cause Pyle disease." (PMID 32328030, 2020). "Loss-of-function mutations in the SFRP4 gene lead to the protein deficiency causing skeletal phenotype typical for Pyle disease." (PMID 33193738, 2020). "With this paper, we have shown that Pyle disease may be related not only to SFRP4 truncating mutations but also to other loss-of-function alterations that possibly impair the protein capacity to bind WNT ligands." (PMID 33193738, 2020). "Herein, we report on the first SFRP4 missense mutations that occurred in compound heterozygosity in two siblings affected by Pyle disease, and which we have identified using a whole-genome sequencing approach followed by a comprehensive in silico pathogenicity assessment." (PMID 33193738, 2020). "As SFRP4 alterations are responsible for Pyle’s disease, a Sfrp4-KO mouse was presented as a model for the disease." (PMID 35052478, 2022). "A disrupted function of sFRP4 was discovered in Pyle disease, a recessive disorder affecting long bones with metaphyseal widening, cortex thinning, increased trabecular bone, decreased bone mineral density, and bone fragility." (PMID 32328030, 2020). "Sfrp4 KO mouse limbs exhibit Erlenmeyer flask deformities observed in Pyle’s disease subjects." (PMID 36808149, 2023). "Bone dysplasias in Pyle’s disease subjects and Sfrp4 KO mice appear during growth and are not progressive in adults." (PMID 36808149, 2023). "Consistent with the autosomal recessive inheritance of Pyle’s disease, except for modestly elevated trabecular bone mass in spine, femur, and tibia, we did not observe skeletal phenotypes in heterozygous Sfrp4 mice." (PMID 36808149, 2023). "There are no apparent bone architecture differences between male and female Pyle’s disease subjects nor Sfrp4 KO mice." (PMID 36808149, 2023).
colon carcinoma (9 papers, 2009 to 2024). "MMPs and signals of Epithelial–Mesenchymal Transition, COMP and SFRP4, were also found to be upregulated in colon cancers and associated with poor overall survival." (PMID 34824625, 2021). "In colon cancer and esophageal adenocarcinoma, SFRP4 gene methylation decreases the inhibition of the Wnt pathway." (PMID 38239300, 2024). "It is possible that SFRP4 is targeted by genetic alterations as it has been described for SFRP1 in colon cancers." (PMID 38993819, 2024). "By comparing with these 65 mRNAs, RSPO3 (ENSG00000146374.12) and SFRP4 (ENSG00000106483.10) in matrix CML(0.7) were found to be related to the occurrence of colon cancer." (PMID 33836755, 2021). "Secreted frizzled related protein 4 (SFRP4) was previously reported to be methylated in colon cancer and was included as a positive control for gene methylation in our study." (PMID 19662090, 2009). "The sFRP4 could compete with Wnt proteins via binding their receptor (Frizzled) to act as an antagonist of the Wnt signaling pathway in colonic cancer." (PMID 34659360, 2021). "Secreted frizzled-related protein 4 (SFRP4), which directly interacts with Wnt proteins and has been suggested as a marker of early-onset colon cancer, was overexpressed in CA tissues." (PMID 35842572, 2022). "They reported that the inhibition of LSD1 in human colon carcinoma cells by biguanide and bisguanidine polyamine analogues resulted in a re-expression of aberrantly silenced genes, including SFRP1, SFRP4, SFRP5, and GATA5." (PMID 23922913, 2013).
coronary artery disease (9 papers, 2014 to 2025). "In clinical research studies, SFRP4 is associated with impaired glucose and triglyceride metabolism in patients with stable coronary artery disease." (PMID 37143778, 2023). "Previous studies have demonstrated that secreted frizzled-related protein 4 (SFRP4) is associated with impaired glucose and triglyceride metabolism in patients with stable coronary artery disease." (PMID 29037197, 2017). "In cases of HF induced by DCM or coronary artery diseases, pro-apoptotic mRNA levels of SFRP4 experience an upsurge." (PMID 40066352, 2025). "In the present study, we investigated human epicardial adipose tissue (EAT)-derived and circulating SFRP4 levels in patients with coronary artery disease (CAD)." (PMID 29037197, 2017). "Here we characterized the relation of SFRP4 to glucose and triglyceride metabolism and outcomes in patients with stable coronary artery disease on statin treatment in the prospective Homburg Cream & Sugar Study (NCT00628524)." (PMID 25408147, 2014). "This prospective study shows that higher SFRP4 concentrations are associated with T2DM and the metabolic syndrome in well-treated patients with coronary artery disease." (PMID 25408147, 2014). "Interestingly, EAT-derived and circulating SFRP4 expression levels are increased in patients with coronary artery disease (CAD)." (PMID 36430774, 2022). "Increased SFRP4 has been reported in patients with coronary heart disease and DCM." (PMID 32423033, 2020). "SFRP4 concentrations are associated with impaired glucose and triglyceride metabolism but do not predict cardiovascular outcome in patients with stable coronary artery disease on treatment." (PMID 25408147, 2014). "Serum SFRP4 levels in patients with stable coronary artery disease (CAD) are also positively correlated with body mass index (BMI), waist circumference and triglycerides, all contributors to metabolic syndrome." (PMID 29037197, 2017). "SFRP4 acts as a soluble modulator of Wnt signaling with elevated expression previously demonstrated in the hearts of patients with DCM and coronary artery disease." (PMID 38727290, 2024). "Secreted frizzled-related protein 4, a novel adipokine which is related to insulin resistance was increased in human EAT samples in patients with coronary artery disease." (PMID 29960588, 2018). "SFRP4 concentrations are a novel marker of impaired glucose and triglyceride metabolism, but do not predict cardiovascular outcome in patients with stable coronary artery disease." (PMID 25408147, 2014).
Insulin resistance (9 papers, 2014 to 2024). Increased resistance towards insulin, that is, diminished effectiveness of insulin in reducing blood glucose levels. "Moreover, the authors presented data showing an association of SFRP4 serum levels with insulin resistance and T2DM." (PMID 25408147, 2014). "This association with HDL-C, along with the positive correlation of HOMA-IR with SFRP4 concentrations suggests an essential role of SFRP4 in developing of insulin resistance." (PMID 38834984, 2024). "Of course, additional work is required to in-depth characterize the relationship between SFRP4 and insulin resistance." (PMID 32657640, 2020). "On the other hand, fat cell enlargement was previously reported as an independent marker of insulin resistance and hyperleptinaemia, and we previously found that circulating SFRP4 protein correlated with measures of adiposity such as body fat and BMI." (PMID 29721017, 2018). "Although circulating SFRP4 levels have been widely recognized as a novel biomarker of β-cell dysfunction, insulin resistance and other metabolic disorders, little is known about serum and EAT-derived SFRP4 expression in patients with CAD." (PMID 29037197, 2017). "The expression of SFRP4 is up-regulated in human visceral white adipose tissue of obese subjects and correlates with increased insulin resistance." (PMID 25408147, 2014). "Thus, the aim of the present study was to evaluate SFRP4 in patients with prediabetes and T2D, as well as its relationship with inflammatory markers (interleukins), to elucidate the role of SFRP4 in insulin resistance as prelude of T2D." (PMID 38834984, 2024). "Additionally, SFRP4 expression is upregulated in obese individuals and is correlated with insulin resistance." (PMID 38834984, 2024). "The serum SFRP4 concentrations were positively correlated with parameters that are elevated in prediabetes and T2D states, such as, HbA1c and homeostasis model assessment insulin resistance (HOMA-IR), (r = 0.168 and 0.248, respectively, P < 0.05)." (PMID 38834984, 2024). "By upregulating secreted frizzled-related protein 4 (SFRP4)—an adipokine which increases insulin resistance by decreasing the abundance of insulin receptor substrate 1 (IRS1) and the FOXO1 transcription factor—these two miRNAs can aggravate insulin resistance in the course of human obesity." (PMID 34943849, 2021). "Moreover, circulating SFRP4 levels are positively correlated with glucose, insulin, glycated hemoglobin and the homeostasis model assessment of insulin resistance (HOMA-IR) values." (PMID 29037197, 2017). "In addition, plasma SFRP4 levels were positively correlated with BMI (r = 0.259, P = 0.030), fasting insulin levels (r = 0.306, P = 0.010) and homeostasis model assessment of insulin resistance (HOMA-IR) values (r = 0.331, P = 0.005)." (PMID 29037197, 2017). "Hence, the SFRP4 protein is related to insulin resistance as an impaired glucose metabolism." (PMID 38834984, 2024). "Some studies have shown a negative correlation between SFRP4 expression and insulin secretion, and plasma levels of SFRP4 have been positively correlated with insulin resistance and negatively correlated with insulin capacity to suppress lipolysis." (PMID 38834984, 2024). "Furthermore, levels of SFRP4 were positively correlated with HOMA-IR, a commonly used method to estimate insulin resistance." (PMID 38834984, 2024).
pancreatic cancer (7 papers, 2014 to 2026). "The association of loss or reduced expression of SFRP4 protein with tumor progression has been documented in esophageal adenocarcinoma, pancreatic cancer, mesothelioma and pituitary adenoma." (PMID 38993819, 2024). "SFRP4 expression was considerably downregulated in pancreatic cancer tissues, and patients with low SFRP4 expression had a better prognosis than those with high SFRP4 expression." (PMID 35847366, 2022). "The mRNA expression levels of SFRP2 and SFRP4 were significantly elevated in the breast, gastric, and pancreatic cancer tissues, while SFRP1 showed significantly decreased expression in datasets from 15 different types of cancer." (PMID 34205081, 2021). "We also explored the relationship between the expression profiles of miR-135b-5p and SFRP4 and the clinicopathological features and prognoses of patients with pancreatic cancer." (PMID 28977937, 2017). "Here, we found that miR-135b-5p was markedly upregulated in pancreatic cancer tissue compared with corresponding adjacent normal tissue, whereas SFRP4 was significantly downregulated." (PMID 28977937, 2017). "In this study, we investigated microRNA and protein expression profiles of miR-135b-5p and SFRP4 using samples from patients with pancreatic cancer." (PMID 28977937, 2017). "The expression of SFRP4 mRNA was also compared between pancreatic cancer tissues and corresponding adjacent normal pancreas in 36 paired primary PDACs using qRT-PCR." (PMID 28977937, 2017). "Future studies are needed to clarify the mechanisms regulating sFRP4 and its role in CP and pancreatic cancer." (PMID 24747916, 2014). "Furthermore, high expression of SFRP4 in the serum and tumor lesions is correlated with shorter overall survival of pancreatic cancer patients." (PMID 34503201, 2021). "The precise cell type-specific role of SFRP4 in pancreatic cancer still need to be elucidated." (PMID 34503201, 2021). "However, on the contrary, another study showed that the expression of SFRP4 was increased in pancreatic cancer lesions in KPC mice and a high expression of SFRP4 was observed in tumor lesions of pancreatic cancer patients." (PMID 34503201, 2021). "In contrast, in the pancreatic cancer tissues, SFRP4 was predominantly negatively expressed in normal ductal epithelial cells, but a small number of cells exhibited weak positivity." (PMID 28977937, 2017). "Neither the role of SFRP4 as an oncogene or tumor suppressor nor its role in the carcinogenesis, progression and outcome of pancreatic cancer has been confirmed." (PMID 28977937, 2017).